DRC12 (dynein regulatory complex subunit 12 homolog)
Description:
Component of the nexin-dynein regulatory complex (N-DRC), a key regulator of ciliary/flagellar motility which maintains the alignment and integrity of the distal axoneme and regulates microtubule sliding in motile axonemes.
Synonyms: CCDC153; LOC283152
Tractability: No criterion of Open Targets' tractability assessment is met for any kind of drug.
Gene: Protein-coding gene on chromosome 11 (119,190,055 to 119,196,769, reverse strand). Ensembl gene ENSG00000248712.
Subcellular location: Cytoplasm, cytoskeleton, flagellum axoneme
Subcellular location (Human Protein Atlas): Cytosol
Gene Ontology:
Molecular function: protein binding
Genetic constraint (gnomAD): Loss-of-function variants: 23 observed, 26.34 expected, observed/expected ratio (o/e) 0.87, 90% interval 0.63 to 1.24. The upper end of that interval is the gene's LOEUF score, 1.24, which puts it in group 5 of 6, group 1 being the genes least tolerant of losing a copy. Missense variants: 241 observed, 276.63 expected, observed/expected ratio (o/e) 0.87, 90% interval 0.78 to 0.97. Synonymous variants: 96 observed, 103.04 expected, observed/expected ratio (o/e) 0.93, 90% interval 0.79 to 1.1.
Homologues: Orthologues: chimpanzee DRC12 (98% identical), macaque DRC12 (92% identical), rabbit DRC12 (74% identical), mouse Ccdc153 (67% identical), guinea pig DRC12 (65% identical), dog CCDC153 (64% identical), pig DRC12 (63% identical), rat Drc12 (60% identical).